ETS1 (ETS proto-oncogene 1, transcription factor)
Diseases named in the same sentence as ETS1 in open-access papers (continued):
Sharing a sentence is not in itself a finding about the gene and the disease.
Arthritis (5 papers, 2006 to 2024). Inflammation of a joint. "We recently identified Ets1 promotes RANKL expression in tissue-destructive synovial fibroblasts in arthritis." (PMID 39080781, 2024). "Through stratified analysis, TNFAIP3 and ETS1 showed significant associations with multiple SLE subphenotypes (such as malar rash, arthritis, hematologic disorder and antinuclear antibody) while TNIP1 just showed relatively weak association with onset age." (PMID 22087647, 2011). "Ets-1 is overexpressed in synovial fibroblasts from arthritis patients and is induced during physiological and pathological angiogenesis." (PMID 16469114, 2006). "As CCN2 plays roles in connective tissue pathologies, targeting Ets-1 may be beneficial in alleviating pathologies of tissue remodeling and repair, including cancer, arthritis and fibrosis." (PMID 16469114, 2006). "Antagonizing Ets-1 might be of benefit in attenuating CCN2 expression in fibrosis, arthritis and cancer, and may be useful in modulating the outcome of these disorders." (PMID 16469114, 2006).
astrocytomas (5 papers, 2009 to 2021). "Furthermore, this study investigated the mechanism underlying the high expression of ETS-1 in astrocytoma tissue." (PMID 34858853, 2021). "The results revealed that the DNMT1-mediated hypermethylation of the miR-338-5p promoter region could participate in the loss of miR-338-5p expression and the high expression of ETS1 associated with disease severity in astrocytoma patients." (PMID 34858853, 2021). "Knockdown or deactivation of DNMT1 decreased the methylation rate of the miR-338-5p promoter, increased the expression of miR-338-5p, and repressed the expression of ETS-1 in astrocytoma cell lines U251 and U87." (PMID 34858853, 2021). "In the present work, aberrant activation of the ETS-1 pathway was identified in high-grade astrocytomas compared with low-grade astrocytomas." (PMID 34858853, 2021). "The expression of miR-338-5p was negatively associated with that of ETS-1 in astrocytoma, and deficiency of miR-338-5p would mediate aberrant expression of ETS-1 in astrocytoma." (PMID 34858853, 2021). "The expression level of ETS-1 in clinical specimens gradually increased from grade I to grade IV astrocytoma, with the highest expression level in grade IV." (PMID 34858853, 2021). "ETS1 is expressed by a variety of solid tumors, including epithelial carcinomas, sarcomas and astrocytomas." (PMID 24602286, 2014). "and would reveal the potential mechanism underlying the high expression of MMPs, that is, the high expression of ETS-1 in astrocytoma tissue may eventually participate in the high expression of MMPs." (PMID 34858853, 2021). "Nevertheless, our results confirmed the expression levels of ETS-1 in tissue specimens of different astrocytoma grades, reflecting the role of ETS-1 in astrocytoma." (PMID 34858853, 2021). "MMPs (matrix metalloproteinases), an invasion-related downstream gene of ETS-1, showed a similar expression trend to that of ETS-1 in astrocytoma." (PMID 34858853, 2021).
B-cell lymphomas (5 papers, 2018 to 2025). "Previous studies have indicated that the gene copy numbers in gastrointestinal tract marginal zone B-cell lymphomas show an increase in ETS1 and a few surrounding genes in the more aggressive large-cell versions of these tumours." (PMID 41162582, 2025). "In contrast to HL, ETS1 and FLI1 are aberrantly upregulated in subsets of DLBCL, pointing to differences in the pathogenesis of these B-cell lymphomas." (PMID 37428779, 2023).
breast tumors (5 papers, 2008 to 2020). "Since breast tumors, differently from other cancer types, more rarely harbor Ras mutations, the S-nitrosylation of Ras and thus the activation of Ets1 signaling axis may indeed explain the wild-type Ras-mediated tumorigenesis of cancers overexpressing NOS2." (PMID 30155439, 2018). "In 2012 Ras was shown to activate Ets-1 transcriptional activity in human ER-negative (ER-) breast tumors." (PMID 30155439, 2018). "Interconnected molecular events orchestrated by ETS1 in breast tumour cells converge to promote invasion of their matrix environment." (PMID 18941460, 2008). "Next, we questioned how breast tumor cells maintain lower ETS1 expression than normal cells." (PMID 32477936, 2020). "However, a recent DNA methylation study has revealed that some ER positive breast tumors exhibit ETS1 demethylation, suggesting that a subset of ER positive tumors express elevated levels of ETS1." (PMID 23874775, 2013). "Moreover, the robust association between NOS2 expression and up-regulation of genes with EBS transcriptional activation sites in microdissected and bulk tumor epithelia indicates that Ets-1 is a significant in vivo mediator of NOS2 signaling in human ER- breast tumors." (PMID 22971289, 2012).
clear cell renal cell carcinoma (5 papers, 2015 to 2026). "Wang determined that miR-377 functions as a tumor suppressor in human clear cell renal cell carcinoma by targeting ETS1." (PMID 26473853, 2015).
lymph node metastasis (5 papers, 2013 to 2025). "Studies indicate that elevated ETS-1 levels correlate with higher tumor grade, greater risk of lymph node metastasis, and shorter patient survival." (PMID 40181983, 2025). "Moreover, ETS1 expression is increased in invasive higher grade tumors, and correlates with a higher incidence of lymph node metastasis." (PMID 26177288, 2015). "ETS1 cytoplasmic levels correlated with the pT status of PTC patients (p = 0.020, r = −0.267), while nuclear levels correlated with the occurrence of lymph node metastasis (p = 0.020, r = −0.271)." (PMID 39941022, 2025). "As it could be seen, cytoplasmic levels of the ETS1 protein correlated with the pT status of PTC patients (p = 0.020, r = −0.267), while the nuclear levels of ETS1 correlated with the lymph node metastasis of the patients (p = 0.020, r = −0.271)." (PMID 39941022, 2025).
renal fibrosis (5 papers, 2018 to 2024). A final common manifestation of a wide variety of chronic kidney diseases characterized by glomerulosclerosis and tubulointerstitial fibrosis. "Hence, Ets-1 has been involved in dermal and renal fibrosis, and targeting this factor showed improvements in collagen dysregulation." (PMID 35008670, 2021). "In fibrosis, miR-221 can induce renal fibrosis through Ets-1." (PMID 31868204, 2020). "In addition, our results indicated that inhibition of ETS-1 could reduce the expression of fibronectin, which was similar to previous findings that angiotensin II induced fibronectin expression and renal fibrosis through ETS-1." (PMID 32799885, 2020). "In these mice, blockade of ETS-1 utilizing a dominant negative peptide (ETS-DN) reduced proteinuria, mesangial expansion and expression of α-smooth muscle actin, a well-validated marker of renal fibrosis." (PMID 29970819, 2018).
triple-negative breast carcinoma (5 papers, 2016 to 2022). An invasive breast carcinoma which is negative for expression of estrogen receptor (ER), progesterone receptor (PR), and human epidermal growth factor receptor 2 (HER2). "In addition, ETS-1 is mainly expressed in triple-negative breast cancer, which is closely associated with poor survival." (PMID 30970566, 2019). "SRC-mediated escape of ETS-1 from COP1 has implications in triple-negative breast cancer (TNBC), where a significant correlation was found in tissue samples between SRC phosphorylation and ETS-1 protein levels." (PMID 34066106, 2021). "Given the downregulated expression of PTPN18 in triple-negative breast cancer cells, it can also be inferred that the degradation of ETS1 regulated by PTPN18 may be one of the reasons that ETS1 is only expressed in triple-negative breast cancer cells." (PMID 35982039, 2022). "Previous research identified ETS-1 as a novel therapeutic target of triple negative breast cancer (TNBC), which does not express ER, progesterone receptor (PR), or HER2 and is associated with a significant risk of poor prognosis and metastasis." (PMID 29312607, 2017).
acute lymphoblastic leukemia (4 papers, 2011 to 2018). Leukemia with an acute onset, characterized by the presence of lymphoblasts in the bone marrow and the peripheral blood. "For example, the HLF motif, which is bound by the hepatic leukemia factor and has been implicated in childhood B-lineage acute lymphoid leukemias, was also found in the intergenic ETS1 peaks." (PMID 21736739, 2011). "Moreover, high expression of miR-221 and miR-222 has been linked to the poor prognostic subtype of human early T cell precursor acute lymphoblastic leukemia (ETP-ALL), and it was discovered that miR-222 directly inhibits the expression of the proto-oncogene ETS1." (PMID 28270163, 2017).
allergic disease (4 papers, 2014 to 2025). An immune response that occurs following re-exposure to an innocuous antigen, and that requires the presence of existing antibodies against that antigen. "These sites are distant from the previously-described T cell-specific super-enhancer region of Ets1, which was reported to be enriched for SNPs associated with allergy." (PMID 40053568, 2025). "Given the critical role of Th17 cytokines in T-cell function and their involvement in the pathogenesis of autoimmune and allergic diseases, Ets-1 has been identified as a key inhibitory transcription factor for Th17 differentiation." (PMID 41310821, 2025). "GWAS data further strengthen the link between these genes and diseases, with BATF, CEBPA, and ETS1 associated with allergic diseases, and PTPN22, ETS1, PTPN11, and BATF linked to RA." (PMID 40839671, 2025).
ankylosing spondylitis (4 papers, 2014 to 2026). An autoimmune chronic inflammatory disorder characterized by inflammation in the vertebral joints of the spine and sacroiliac joints. "We aimed to investigate whether polymorphisms in ETS1 confer susceptibility to ankylosing spondylitis (AS) in Han Chinese." (PMID 24708692, 2014).
brain cancer (4 papers, 2015 to 2023). A primary or metastatic malignant neoplasm affecting the brain. "Furthermore, inhibition of ETS1 might be of therapeutic interest in the context of brain cancer or neurodegenerative diseases in which insufficient immune responses in the CNS can contribute to pathology." (PMID 37709997, 2023). "The ETS1 transcription factor has no characterized role in human neural induction, although it is expressed in normal brain cells and in brain cancers, where it regulates cell migration and invasion." (PMID 25978676, 2015).
diabetic nephropathy (4 papers, 2021 to 2026). "ETS1 plays an important role in diabetic nephropathy and hypertensive nephropathy-related renal damage." (PMID 35611792, 2022).
liver fibrosis (4 papers, 2019 to 2025). "ETS-1 is linked to liver fibrosis, where it is thought to be activated by Extracellular Signal-Regulated Kinases (ERK) signalling pathways, matrix remodelling, and cross talk with Transforming Growth Factor (TGF)-Suppressor of Mothers Against Decapentaplegic (SMAD) signalling." (PMID 38474099, 2024). "Here, we investigated the role of ETS1/2 in HSCs in liver fibrosis using toxic liver injury models and 3D human liver spheroids." (PMID 41196693, 2025). "Regression of liver fibrosis was suppressed only in Ets1ΔHSC mice, indicating Ets1 is the predominant isoform maintaining a quiescent-like phenotype in HSCs." (PMID 41196693, 2025). "Moreover, hematoxylin and eosin (H&E) staining, F4/80 immunofluorescence staining, and Sirius Red staining of liver sections showed that the downregulation of Ets-1 significantly ameliorated liver fibrosis and inflammation induced by the MCD diet." (PMID 31189885, 2019). "However, the role of Ets-1 in promoting or inhibiting liver fibrosis remains controversial." (PMID 34820381, 2021). "Accordingly, future studies on the role of Ets-1 in liver fibrosis may be of great significance." (PMID 31189885, 2019). "Liver fibrosis was induced in WT and HSC-specific Ets1-KO (Ets1ΔHSC) and Ets2-KO (Ets2ΔHSC) mice by administration of CCl4 for 6 weeks, followed by cessation of liver injury for 2 weeks." (PMID 41196693, 2025). "However, it has been reported that Ets-1 suppresses the production of ECM by down-regulating matrix related genes such as COL1A1 induced by TGF-β, and ultimately inhibit liver fibrosis." (PMID 34820381, 2021). "In conclusion, this study indicates that rSjP40 inhibits the activity of COL1A1 promoter by increasing the expression of transcription factor Ets-1, down-regulating the expression of COL1A1, thereby inhibiting the activation of HSCs and inhibiting liver fibrosis." (PMID 34820381, 2021). "In addition, studies have found that Ets proto-oncogene 1 (Ets-1) suppresses the production of ECM by down-regulating matrix related genes such as COL1A1 induced by transforming growth factor β, and ultimately inhibits liver fibrosis." (PMID 34820381, 2021).
metastatic tumor (4 papers, 2017 to 2025). "It was observed that the majority of mice injected with control cells developed distal metastases (87.5%), whereas only 25% of mice injected with ETS1-knockdown cells exhibited metastatic disease (P = 0.04)." (PMID 40777467, 2025). "Strikingly, while only 11% of mice injected with control cells developed detectable metastases, 100% of mice injected with ETS1-overexpressing cells exhibited widespread metastatic disease (P = 0.0004)." (PMID 40777467, 2025). "The expression level upregulation of the genes might be mediated by TFs, such as POLR3D, NOTCH1 and ETS1, which were widely expressed at high levels in bone metastatic tumor samples." (PMID 38462627, 2024).
oral cancer (4 papers, 2010 to 2023). "Ets-1 is also expressed only in the basal layer of stratified squamous epithelium of normal tissue and sufficient to induce invasion especially for oral cancer." (PMID 28672814, 2017). "Accordingly, the TGFβ1/Smad 2/3 axis regulates MMP-9 expression through the transcriptional factors Snail and Ets-1, contributing to oral cancer progression." (PMID 20462450, 2010).
papillary thyroid carcinoma (4 papers, 2021 to 2025). "The present study investigates the interplay between p16 promoter methylation status, the BRAFV600E mutation, and ETS1 gene and protein expression in patients with papillary thyroid carcinoma (PTC)." (PMID 40722658, 2025). "The expressions of ETS1, miR-203a-3p, and miR-204-3p in papillary thyroid carcinoma (PTC) are poorly described, and their clinical significance is unclear." (PMID 39941022, 2025). "In papillary thyroid carcinoma, expression of ITPR1 was promoted via effect of lncRNA SLC26A4-AS1 mediated ETS1 recruitment, suppressing tumour growth by enhancing autophagy." (PMID 35459137, 2022).
pulmonary fibrosis (4 papers, 2015 to 2021). Chronic progressive interstitial lung disorder characterized by the replacement of the lung tissue by connective tissue, leading to progressive dyspnea, respiratory failure, or right heart failure. "The expression of EMT markers, fibronectin, ETS-1 and pulmonary fibrosis was observed in PMs-treated mice." (PMID 32799885, 2020). "In this study, a significant correlation between fibronectin and ETS-1 expression was further demonstrated in the tissue array analysis of patients with pulmonary interstitial fibrosis." (PMID 32799885, 2020). "The aim of this study was to investigate the effects of O-PMs on the pathogenesis of EMT and pulmonary fibrosis as well as the expression of ETS-1 and NF-κB p65, in vitro and in vivo." (PMID 32799885, 2020). "There was a significant correlation between fibronectin and ETS-1 expression in human pulmonary fibrosis tissue." (PMID 32799885, 2020). "Furthermore, we examined the relationship between ETS-1 and fibronectin expression in human pulmonary interstitial fibrosis by using a human tissue microarray." (PMID 32799885, 2020). "We also showed that the expression of ETS-1 and fibronectin is closely related in organic solvent soluble PMs (O-PMs)-treated A549 cells, the lung tissues of PMs-treated mice, and the lung tissues of patients with pulmonary fibrosis." (PMID 32799885, 2020). "Bleomycin-induced pulmonary fibrosis is contributed by type II alveolar epithelial-derived fibroblasts through EMT induction, while PM exposure also induces EMT and fibronectin expression, and activation of transcription factors ETS-1 and NF-κB." (PMID 33706759, 2021). "All these findings suggest that the ETS-1 pathway may be a novel alternative pathway for EMT formation and pulmonary fibrosis." (PMID 32799885, 2020). "The most important and novel finding is that the ETS-1 pathway may be important in the pathogenesis of EMT and pulmonary fibrosis." (PMID 32799885, 2020). "The roles of ETS-1 and p-p65 in the pathogenesis of EMT and pulmonary fibrosis have not been determined." (PMID 32799885, 2020).
sarcoma (4 papers, 2014 to 2023). A usually aggressive malignant neoplasm of the soft tissue or bone. "Together, our studies reveal an important role for the KDM3A/Ets1/MCAM axis in pediatric sarcomas of distinct cellular and molecular ontogeny, and identify new targetable vulnerabilities in RMS." (PMID 32577157, 2020). "However, high ETS1 level was associated with short OS in KIRP (HR = 2.24, 95% CI: 1.22-4.11), sarcoma (SARC; HR = 1.57, 95% CI: 106-2.34), and PAAD (HR = 1.65, 95% CI: 1.06-2.57)." (PMID 36760475, 2023). "The manner in which Ets1 regulation by PAX3/FOXO1 and EWS/Fli1 tracks with the effects of the respective oncofusions on metastatic phenotypes suggests that Ets1 may have a more general, important role in sarcoma metastasis." (PMID 32697014, 2020).
Sepsis (4 papers, 2021 to 2025). Sepsis is defined as life-threatening organ dysfunction caused by a dysregulated host response to infection. "Our study confirmed the promoting role of ETS1 in the pathogenesis of sepsis-associated AKI." (PMID 35611792, 2022). "Interestingly, late sepsis activated CD4+ T cells had high expression of ETS1, which has been implicated as a negative regulator of Th17 differentiation." (PMID 34484194, 2021). "We further found that the deletion of ETS1 significantly inhibited LPS-induced EC activation, suggesting the potential involvement of ETS1 in fatty acid synthesis-related EC dysfunction in sepsis." (PMID 40369168, 2025). "Proteins that interacted with ETS1 in HUVEC were screened to explore the mechanisms of ETS1 in regulating mtDNA release in ECs during sepsis." (PMID 40369168, 2025). "The deletion of ETS1 in HUVEC effectively inhibited the upregulations of VCAM-1, E-selectin, PAI-1, and TF induced by LPS in both protein and mRNA levels, suggesting the regulatory importance of ETS1 in EC activation during sepsis." (PMID 40369168, 2025). "Collectively, we discovered for the first time that fatty acid synthesis promoted mtDNA release-related EC dysfunction via ETS1-mediated VDAC1 ubiquitination and oligomerization, thereby leading to the lung injury in sepsis." (PMID 40369168, 2025). "Both PPI and lncRNA-miRNA-mRNA networks confirmed that ETS proto-oncogene 1 (ETS1), C-C motif chemokine receptor 7 (CCR7) and CD5 are key genes of the ceRNA network in sepsis." (PMID 36457745, 2022). "The sub analysis of healthy versus CCI CD4+ T-lymphocytes revealed unique differential expression of five genes not seen in the analysis of all late sepsis patients (upregulated: HBB, ETS1; downregulated: SMDT1, RPL41, MTRNR2L12)." (PMID 34484194, 2021).
Thrombocytopenia (4 papers, 2008 to 2025). A reduction in the number of circulating thrombocytes. "ETS1 encodes a transcription factor from the ETS family, which has been proposed to be involved in hematopoiesis, thrombocytopenia, pancytopenia and even in the formation of micromegakaryocytes." (PMID 34440371, 2021).